ERCC1 (ERCC excision repair 1, endonuclease non-catalytic subunit)
Diseases named in the same sentence as ERCC1 in open-access papers (continued):
Sharing a sentence is not in itself a finding about the gene and the disease.
ischemic stroke (1 paper, 2022). A stroke disorder caused by obstruction of blood flow to the brain, due to thrombotic (local blood clot formation) or embolic (due to a blood clot or other material traveling from another site) event. "In the current study, we conducted a case-control study to detect ERCC1 mRNA and protein levels and evaluated associations between the ERCC1 rs3212986 polymorphism and ischemic stroke susceptibility in the Chinese Han population." (PMID 36712419, 2022). "Nevertheless, the significant associations between ERCC1 rs3212986 polymorphism and ischemic stroke susceptibility still remained after adjusting for the age factor." (PMID 36712419, 2022). "There was the first evidence that A allele of the ERCC1 rs3212986 polymorphism was associated with increased ischemic stroke risk." (PMID 36712419, 2022). "It was suggested that the ERCC1 rs3212986 polymorphism was associated with ischemic stroke susceptibility in a Chinese Han population and that an A allele of rs3212986 was related to increased ischemic stroke risk." (PMID 36712419, 2022). "The association between the ERCC1 rs3212986 polymorphism or its expression and ischemic stroke was further analyzed." (PMID 36712419, 2022). "The association between the ERCC1 rs3212986 polymorphism and ischemic stroke susceptibility was found in both recessive (OR = 2.638, 95% CI = 1.744–3.989, P < 0.001) and additive (OR = 1.309, 95% CI = 1.028–1.667, P = 0.031) models, respectively." (PMID 36712419, 2022). "Nevertheless, there was little information about the association of ischemic stroke susceptibility with the rs3212986 polymorphism located in the 3'-UTR of ERCC1 and strongly related to altering its mRNA and protein expression." (PMID 36712419, 2022). "The findings indicated that ERCC1 rs3212986 polymorphism was associated with ischemic stroke susceptibility in a Chinese Han population, and A allele of rs3212986 might be related to increasing ischemic stroke risk." (PMID 36712419, 2022). "Association between ERCC1 rs3212986 polymorphism and ischemic stroke susceptibility." (PMID 36712419, 2022). "The altered ERCC1 mRNA expression level caused by the ERCC1 rs3212986 polymorphism might participate in the pathophysiological process of ischemic stroke." (PMID 36712419, 2022). "The altered ERCC1 expression level caused by the rs3212986 polymorphism might participate in the pathophysiological process of ischemic stroke." (PMID 36712419, 2022). "Excision repair cross-complementing group 1 (ERCC1) was considered a potential candidate gene for ischemic stroke, and its polymorphisms might be associated with the susceptibility to ischemic stroke." (PMID 36712419, 2022). "It was suggested that A allele of the ERCC1 rs3212986 polymorphism might be a risk factor for ischemic stroke." (PMID 36712419, 2022). "Therefore, we hypothesized that ERCC1 polymorphism and its expressions may also be associated with ischemic stroke risk." (PMID 36712419, 2022). "This study indicated that the A allele of ERCC1 rs3212986 was associated with increased ischemic stroke risk, and the altered ERCC1 mRNA expression level caused by the ERCC1 rs3212986 polymorphism might participate in the pathophysiological process of ischemic stroke." (PMID 36712419, 2022). "The ERCC1 mRNA level in patients with ischemic stroke was lower than that in the control group (P < 0.05)." (PMID 36712419, 2022). "The ERCC1 mRNA relative expression levels in patients with ischemic stroke and controls were 1.02 ± 0.18 and 1.60 ± 0.19, respectively." (PMID 36712419, 2022). "Furthermore, mice with ERCC1 deficiency also had elevated serum cholesterol level and change in the expression of genes involved in the metabolism of cholesterol, which were associated with vascular stiffness and have been considered traditional risk factors for ischemic stroke." (PMID 36712419, 2022). "The ERCC1 mRNA's relative expression level in patients with ischemic stroke was lower than that in the control group (P = 0.027)." (PMID 36712419, 2022).
ischemic stroke (continued). "In the current study, a lower relative expression level of ERCC1 mRNA in patients with ischemic stroke was observed." (PMID 36712419, 2022). "There was the first evidence that ERCC1 has a protective role in the pathophysiological process of ischemic stroke in the MCAO rat." (PMID 36712419, 2022). "Therefore, the ERCC1 rs3212986 polymorphism may alter its mRNA and protein expression and promote endothelial cell dysfunction, vascular senescence, and plaque rupture, which eventually contribute to accelerated vascular stiffness and increased ischemic stroke risk." (PMID 36712419, 2022). "However, the ERCC1 protein level in patients with ischemic stroke was higher than that in the control group (P < 0.05)." (PMID 36712419, 2022). "However, the level of ERCC1 protein in ischemic stroke patients (0.41 ± 0.04 ng/mL) was higher than that in controls (0.29 ± 0.01 ng/ml) (P < 0.001)." (PMID 36712419, 2022). "The transcription might be weak, even would not be induced or activated due to ERCC1 deficiency, if there were severe ischemia, hypoxia, and stress stimulation in patients with ischemic stroke." (PMID 36712419, 2022). "The ERCC1 rs3212986 polymorphism, located on the 3'-UTR of the ERCC1 gene, has been widely studied in previous studies and might be involved in the potential pathophysiological mechanism in ischemic stroke." (PMID 36712419, 2022). "It was suggested that ERCC4, as an important component of the ERCC1/ERCC4 heterodimer and a rate-limiting enzyme in the NER pathway, might play a key role in the pathophysiological process of ischemic stroke and that its variations were likely to increase ischemic stroke risk." (PMID 36712419, 2022).
laryngeal squamous cell carcinoma (1 paper, 2019). A squamous cell carcinoma that arises from the larynx. "Analysis of laryngeal squamous cell carcinoma showed an association with lower susceptibility risk in ERCC1 rs11615 and ERCC2 rs13181 SNPs." (PMID 30959967, 2019).
malignant brain tumor (1 paper, 2022). "There is a difference in the expression of excision-repair cross-complementation group 1 (ERCC1) mRNA between non-tumor brain tissues and malignant brain tumor tissues." (PMID 35674307, 2022).
medulloblastoma (1 paper, 2018). A malignant, invasive embryonal neoplasm arising from the cerebellum. "Conversely, relatively low expression frequency of the excision repair cross-complementation group 1 (ERCC1), which a predictive biomarker of cisplatin-based chemotherapy resistance would indicate current use of cisplatin for medulloblastoma treatment is justifiable in most cases." (PMID 29869738, 2018).
meningioma (1 paper, 2015). A generally slow growing tumor attached to the dura mater. "The aim of this study was to evaluate the methylation status of 12 cancer-related genes, namely ERCC1, hMLH1, ATM, CDKN2B (p15INK4B), p14ARF, CDKN2A (p16INK4A), RASSF1A, RUNX3, GATA6, NDRG2, PTEN, and RARβ, in 44 meningioma samples of WHO grade I and II." (PMID 25648363, 2015).
myocardial infarction (1 paper, 2023). Gross necrosis of the myocardium, as a result of interruption of the blood supply to the area, as in coronary thrombosis. "In contrast, reduced expression of numerous DNA repair genes, including ERCC1, XPA, and ATM, are associated with stable angina and myocardial infarction." (PMID 36734200, 2023).
nephropathies (1 paper, 2020). "In fact, ERCC1 and ERCC4 play important roles in the development of nephropathies, as demonstrated in mammalian models." (PMID 31924810, 2020).
ovarian clear cell cancer (1 paper, 2020). An invasive malignant neoplasm that arises from the ovary and is characterized by a predominance of clear and hobnail malignant epithelial cells. "Meanwhile, genes involved in nucleotide excision repair (such as XPB and ERCC1), were found to be preferentially expressed in ovarian clear cell carcinomas." (PMID 32160916, 2020).
peritoneal effusion (1 paper, 2011). "In this study, we have investigated the immunochemical performance of the 2 mouse monoclonal anti-ERCC1 antibodies 8F1 and D-10 on cell blocks of malignant pleural and peritoneal effusions assembled together with histologic control cores to hybrid C/TMAs." (PMID 21961533, 2011). "Therefore, we evaluated the staining quality of monoclonal anti-ERCC1 antibodies 8F1 and D-10 on microarrays of malignant pleural and peritoneal effusions by automated immunochemistry." (PMID 21961533, 2011). "We concluded that cells from most common malignancies giving rise to pleural or peritoneal effusion display a robust ERCC1 protein expression and that no particular entity has completely lost expression of this enzyme." (PMID 21961533, 2011).
Pleural effusion (1 paper, 2008). The presence of an excessive amount of fluid in the pleural cavity. "Both ERCC1 and BRCA1 were negatively correlated with cisplatin sensitivity in pleural effusions of NSCLC patient." (PMID 18402708, 2008).
pneumoconiosis (1 paper, 2024). An occupational lung disorder caused by inhalation of dust particles. "When ERCC1 concentration reaches cut-off value, workers should leave the workplace and change other jobs and will failure to develop and diagnose pneumoconiosis." (PMID 39283905, 2024).
prostate tumors (1 paper, 2017). "Under the selected experimental conditions, detectable ERCC1 staining was found in 65% of prostate tumors." (PMID 28747165, 2017).
renal dysfunction (1 paper, 2018). "Cases of renal dysfunction were more prevalent among patients with the ERCC1 gene rs11615 heterozygous T/C (46.7%) with OR = 2.51 (95% CI 1.09–5.57; p = 0.037) and rs3212986 heterozygous C/A (52.8%) genotypes with OR = 3.29 (95% CI 1.40–7.73; p = 0.009) compared with the homozygous variants." (PMID 30319427, 2018).
retinal degeneration (1 paper, 2025). Degeneration of the retina. "Therefore, Ercc1−/Δ mice represent a valuable model for further mechanistic studies on age‐related retinal degeneration and for rapid testing of potential therapeutic interventions." (PMID 39604117, 2025).
skin cancer (1 paper, 2015). "Keratinocyte-specific deletion of the gene encoding ERCC1 in mice causes hypersensitivity to UV-induced skin cancer, demonstrating the critical role of this enzyme in repairing UV-induced DNA damage." (PMID 26404324, 2015).
Sleep apnea (1 paper, 2017). An intermittent cessation of airflow at the mouth and nose during sleep is known as sleep apnea. "To conclude, this first meta-analysis of symptoms of sleep apnea using WES data identified a rare genetic variant, rs2229918 (MAF 0.3%), located in the 3′-UTR of ERCC1 and CD3EAP, associated with symptoms of sleep apnea." (PMID 29093733, 2017). "Suggestive associations of symptoms of sleep apnea were observed with 11 rare variants (located in KANK2, LCN6, TRAF3, PLEK, HIF1A, SLC45A3, ERCC1/CD3EAP, MRGPRE, GRAMD4, TYW5, CST5)." (PMID 29093733, 2017). "We identified a rare genetic variant (MAF = 0.3%), rs2229918, located in the shared 3′-UTR region of the ERCC1 and CD3EAP genes with a large effect on symptoms of sleep apnea." (PMID 29093733, 2017). "This further supports that ERCC1 and CD3EAP are interesting candidate genes for symptoms of sleep apnea." (PMID 29093733, 2017).
stomatitis (1 paper, 2020). Inflammation of the oral mucosa due to local or systemic factors. "The ERCC1-rs11615 genotype T/T was significantly associated with stomatitis during adjuvant treatment, while among patients receiving first-line chemotherapy, the ERCC1-rs11615 C allele was associated with nausea." (PMID 32397974, 2020). "In our study of patients receiving adjuvant FLV or FLOX therapy, the ERCC1-rs11615 genotype T/T was significantly associated with stomatitis, and among patients receiving first-line chemotherapy, the ERCC1-rs11615 C allele was associated with nausea." (PMID 32397974, 2020). "The ERCC1-rs11615 genotype T/T was associated with stomatitis in adjuvant chemotherapy (p = 0.03)." (PMID 32397974, 2020). "In patients receiving adjuvant chemotherapy, the ERCC1-rs11615 genotype T/T was significantly associated with stomatitis (p = 0.03), and significantly more patients with the ERCC2-rs13181 C allele needed dose reduction compared to patients with the A/A genotype (p = 0.02)." (PMID 32397974, 2020).
testicular germ cell tumor (1 paper, 2020). A germ cell tumor arising from the testis. "The ERCC1 and XPA genes in the NER pathway have confirmed that ERCC1 is associated with metastasis in testicular germ cell tumors, and high expression of ERCC1 will lead to an increased risk of metastasis." (PMID 33184404, 2020).
thymic tumor (1 paper, 2015). "We aimed to analyze genotypes of VEGF-A, VEGFR2, Flt4, PDGFRα, HIF-1α and ERCC1 and their correlation with thymic tumor risk and patient outcome." (PMID 26254278, 2015).
toxicity (1 paper, 2025). The degree to which an agent can damage an organism. "In fact, a tendency for association of the ERCC1 c.354TT genotype with renal toxicity (p‐value = 0.06), using 51Cr‐EDTA, had already been identified in a preliminary analysis of this cohort of patients (n = 90)." (PMID 40342074, 2025).
transitional cell carcinoma of the bladder (1 paper, 2012). "Among patients with completely resected transitional cell carcinoma of the bladder, those with ERCC1-negative tumors seemed to benefit more from adjuvant gemcitabine plus cisplatin chemotherapy than those with ERCC1-positive tumors." (PMID 22616552, 2012). "Among patients with transitional cell carcinoma of the bladder treated with cystectomy, high tumoral expression of ERCC1 correlated with longer survival in patients without adjuvant chemotherapy and was associated with shorter survival in those with adjuvant chemotherapy." (PMID 22616552, 2012).
vascular tumor (1 paper, 2022). "ERCC1 expression [P <0.001, HR = 13.403 (2.921–61.429)] and vascular tumor thrombus [P < 0.05, HR = 3.174(1.248–8.073)] were independent influencing factors that influence OS." (PMID 36338712, 2022). "ERCC1 expression and vascular tumor thrombus were independent influencing factors that influence OS." (PMID 36338712, 2022). "However, a significant correlation (P < 0.05) was observed between the ERCC1 and ER expression, vascular tumor thrombus, chemotherapy, and DFS." (PMID 36338712, 2022).
Werner syndrome (1 paper, 2009). "Significant age-related methylation alterations in telomere maintenance gene-loci TERT, ERCC1, RAD50, and the Werner syndrome gene-locus (WRN) were also observed." (PMID 19680444, 2009).
tumor (261 papers, 2005 to 2025). "Other molecular markers have been postulated for platinum-based chemotherapy in NSCLC, such as excision repair cross-complementation group 1 (ERCC1) protein expression in tumor tissue and ERCC1 germline polymorphisms." (PMID 40362483, 2025). "In both cases, a hypermethylation of MGMT and ERCC-1 promoter was associated with decreased tumor regression." (PMID 36766755, 2023). "ERCC1 rs11615 mutation has different correlations in different parts of the tumor, and there is a certain degree of disagreement even in the same tumor." (PMID 36277013, 2022). "ERCC1 gene polymorphism is not only associated with tumor susceptibility but also with the efficacy of platinum drugs' treatment in various tumors." (PMID 36277013, 2022). "Mechanistically, we performed tumour chemosensitivity assay to observe the convincing linkage of rs3212986 polymorphism with ERCC1 expression and cisplatin sensitivity." (PMID 36181289, 2022). "In order to verify the clinical relevance of ERCC1 rs3212986 polymorphism, the primary tumour cells from NSCLC patients were cultured and attacked with CDDP to evaluate the individual sensitivity to platinum analogues." (PMID 36181289, 2022). "Low levels of ERCC1 have been shown to be correlated with high tumor mutational burden, which confers favorable response to immunotherapy in aUC treatment." (PMID 34898581, 2021). "PD‐L1 expression and ERCC1 positive were associated in 3 of 39 tumor types; hence, combinations of platinum and immunotherapy are not beneficial." (PMID 31479512, 2020). "While enhanced sPD-L1 was associated with residual tumor burden (p = 0.022), reduced sPD-L2 levels were related to platinum-resistance (p < 0.01) and the presence of ERCC1+ CTCs (p < 0.0001)." (PMID 31681568, 2019). "On the other hand, in ER− tumours that received chemotherapy, low ERCC1 protein was linked to improved disease relapse free survival (p = 0.034))." (PMID 31405143, 2019). "A low level of ERCC1 transcript was significantly associated with higher grade cancer, whereas low grade tumours were common in high ERCC1 tumours (p values < 0.0001)." (PMID 31405143, 2019). "In ER− tumours, low ERCC1 transcript or protein level was linked to decreased DRR, especially in patients who received anthracycline chemotherapy." (PMID 31405143, 2019). "In ER+ tumours, low ERCC1 transcript or protein level was associated with increased distant relapse risk (DRR)." (PMID 31405143, 2019). "Increased ERCC1 tumor mask and XPF nuclear expression were associated with an improved DFS (HR 0.30 (95% CI: 0.09–0.97), p=0.044; HR 0.01 (95% CI: 0.00–0.92), p=0.046, resp)." (PMID 29681762, 2018). "High levels of ERCC1 staining were significantly linked to increased tumor cell proliferation measured as Ki67 labeling index (Ki67LI) (p < 0.0001)." (PMID 28747165, 2017). "ERCC1 staining was similarly linked to unfavorable tumor phenotype in subsets of both ERG-negative and ERG-positive cancers." (PMID 28747165, 2017). "More broadly, an association between ERCC1 expression and cisplatin response has also been reported in other tumor types, although many of these studies lack prospective validation or have suffered from difficulties with reproducibility." (PMID 28346378, 2017). "NPC prognosis has been found to be associated with some biomarkers based on individual tumor characteristics: such as Epstein-Barr virus DNA, epidermal growth factor receptor and ERCC1." (PMID 27549330, 2016). "ERCC1+ samples showed an allelic distribution with most being homozygous for the major allele (CC = 59%), a trend also observed from ERCC1− tumor samples (CC = 59.2%)." (PMID 25191856, 2014). "We therefore studied pleural effusions with respect to the drug sensitivity of tumor cells and immunoreactivity of two proteins associated with drug resistance, ERCC1 and RRM1." (PMID 25253633, 2014).